MTERF4 (mitochondrial transcription termination factor 4)
Description:
Regulator of mitochondrial ribosome biogenesis and translation. Binds to mitochondrial ribosomal RNAs 16S, 12S and 7S and targets NSUN4 RNA methyltransferase to the mitochondrial large ribosomal subunit (39S).
Synonyms: MTERFD2; MGC61716
Tractability: Small molecule: a structure with a bound ligand is known. PROTAC: ubiquitination databases record sites on it; its protein half-life has been measured.
Gene: Protein-coding gene on chromosome 2 (241,072,169 to 241,102,332, reverse strand). Ensembl gene ENSG00000122085.
Subcellular location: Mitochondrion
Subcellular location (Human Protein Atlas): Cytosol; Mitochondria
Pathways (Reactome):
Metabolism of RNA: rRNA modification in the mitochondrion
Gene Ontology:
Molecular function: protein binding; protein-RNA adaptor activity; RNA folding chaperone; rRNA binding; nucleic acid binding
Biological process: mitochondrial large ribosomal subunit assembly; rRNA processing; mitochondrial ribosome assembly; RNA folding
Cellular component: mitochondrion; mitochondrial matrix
Genetic constraint (gnomAD): Loss-of-function variants: 17 observed, 24.59 expected, observed/expected ratio (o/e) 0.69, 90% interval 0.47 to 1.04. The upper end of that interval is the gene's LOEUF score, 1.04, which puts it in group 4 of 6, group 1 being the genes least tolerant of losing a copy. Missense variants: 420 observed, 488.38 expected, observed/expected ratio (o/e) 0.86, 90% interval 0.79 to 0.93. Synonymous variants: 165 observed, 184.47 expected, observed/expected ratio (o/e) 0.89, 90% interval 0.79 to 1.02.
Homologues: Orthologues: chimpanzee MTERF4 (96% identical), macaque MTERF4 (87% identical), guinea pig MTERF4 (64% identical), pig MTERF4 (61% identical), rat Mterf4 (59% identical), mouse Mterf4 (59% identical), dog MTERF4 (31% identical), zebrafish mterf4 (31% identical), tropical clawed frog mterf4 (26% identical), Caenorhabditis elegans mter-4 (19% identical), Drosophila melanogaster CG15390 (16% identical).
Diseases named in the same sentence as MTERF4 in open-access papers:
MTERF4 is named in the same sentence as 10 diseases in open-access papers, as found by Europe PMC text mining. Sharing a sentence is not in itself a finding about the gene and the disease. The quoted sentences say what the papers report.
cardiomyopathy (1 paper, 2021). A disease of the heart muscle or myocardium proper. "The pathological significance of GTPBP7, MTERF4, and NSUN4 is demonstrated by their association with cardiomyopathy, which is a common feature of mitochondrial diseases." (PMID 34609277, 2021).
hypertrophic cardiomyopathy (1 paper, 2021). A condition in which the myocardium is hypertrophied without an obvious cause. "Variant alleles of MTERF4 have also been documented in a pediatric patient with hypertrophic cardiomyopathy." (PMID 34609277, 2021).
Vertigo (1 paper, 2022). An abnormal sensation of spinning while the body is actually stationary. "MTERFD2, also known as MTERF4, is another vertigo risk gene identified in this study that belongs to the component of the mitochondrial transcription termination factor (MTERF) family." (PMID 36519156, 2022).
cancer (2 papers, 2023 to 2024). A tumor composed of atypical neoplastic, often pleomorphic cells that invade other tissues. "The MTERF family includes MTERF1, MTERF2, MTERF3, and MTERF4 that have roles in the pathogenesis of various cancer types." (PMID 38324544, 2024).
tumor (1 paper, 2024). "Furthermore, the expression of MTERF4 is essential for tumor cell proliferation, and knocking down MTERF4 in HeLa cells leads to sub-G1 cell accumulation and apoptosis." (PMID 38589371, 2024).
MTERF4 also shares sentences with these, for which no sentence is quoted: Leigh syndrome (1 paper); lung carcinoma (1); mitochondrial disease (1); neurodegenerative disease (1); rectal cancer (1).